STAT3 (signal transducer and activator of transcription 3)
Diseases named in the same sentence as STAT3 in open-access papers (continued):
Sharing a sentence is not in itself a finding about the gene and the disease.
oral cancer (continued). "To verify the functional role of STAT3 in oral cancer cell lines, we used cryptotanshinone (Crypto), a potent STAT3 inhibitor." (PMID 29207645, 2017). "Our recent study showed that sorafenib, an oral multi-kinase inhibitor, inactivates the STAT3 signaling pathway to suppress mucoepidermoid carcinoma (one type of oral cancer) in vitro and in vivo." (PMID 29207645, 2017). "Immunoblot analysis of HPV‐positive and HPV‐negative oral cancer tissues demonstrated an increased expression of STAT3 and pSTAT3 with reference to the control tissues." (PMID 28155253, 2017). "Our results showed that either NC or a STAT3 inhibitor inactivated the STAT3 signaling pathway to suppress cell viability and induce apoptosis in human oral cancer cell lines." (PMID 29207645, 2017). "Next, overall relationship between STAT3/pSTAT3 expression, positive (pEGFR) and negative regulators (p16) of STAT3 signaling, and individual AP‐1 and NF‐κB members in the oral cancer lesions was examined." (PMID 28155253, 2017). "EGFR is a membrane bound tyrosine kinase receptor, which phosphorylates MEK/Erk, STAT3, and mTOR signal molecules for regulation of cell survival and mitosis in many types of malignancy, including oral cancer." (PMID 29212184, 2017). "In the present study, we clearly demonstrated that STAT3 was significantly activated in OSCC compared to NOM implying that activation of STAT3 plays a critical role in the development of oral cancer." (PMID 29207645, 2017). "We also performed the effects of NC on cell viability, apoptosis and STAT3 phosphorylation in four different oral cancer cell lines." (PMID 29207645, 2017). "NC also suppressed cell viability and induced apoptosis accompanied by dephosphorylating STAT3 in four other oral cancer cell lines." (PMID 29207645, 2017). "Together, S100A9 increased IL-6 production through the cross-talk of oral cancer cells with monocytes and the activation of NF-κB or STAT-3 participated in the release." (PMID 26315114, 2015). "By the experiments in which IL-6 signaling was suppressed by IL-6 antibody, we found that activated IL-6 signaling plays an important role in DNMT3b activation associated with activated STAT3 and PI3K in oral cancer cells." (PMID 24625449, 2014). "STAT3 is a potent inducer of PD-L1 expression in oral cancers to explore whether STAT3 promotes immune evasion via PD-L1 expression, we transfected OSCC cells with either a STAT3 expression plasmid or STAT3 siRNA." (PMID 40140827, 2025). "The JAK1/STAT3 signalling pathway inhibitor niclosamide also inhibited VM in oral cancer." (PMID 38459564, 2024). "Other studies have highlighted the importance of the JAK/STAT-3 pathway in oral cancer, where malvidin acts as a STAT-3 inhibitor in the SCC13 oral cancer cell line, inhibiting STAT-3 phosphorylation and nuclear translocation, thereby inducing cell cycle arrest and mitochondrial-mediated apoptosis." (PMID 39334802, 2024). "Consequently, autophagy is induced by AMPK activation, and the cell cycle is decreased by dephosphorylation of STAT3, leading to apoptosis of oral cancer cells through the activation of p38 MAPK and NF-κB." (PMID 38720012, 2024). "The nuclear accumulation of PD-L1 in oral cancer cells was activated-STAT3-dependent." (PMID 36231010, 2022). "The development and early clinical trials of PROTACs is an encouraging next phase in the search for STAT3 inhibitors that may yet provide clinical benefit for STAT3-driven cancers such as gastric and oral cancers." (PMID 35844493, 2022). "Furthermore, it inhibits nuclear translocation of STAT3, prevents proliferation, induces apoptosis of oral cancer cells in vitro and in vivo." (PMID 34539403, 2021). "In conclusion, our findings suggest that overexpression of IL-6 and IL-8 promotes the EMT and invasion abilities of oral cancer cells through the STAT3 signaling pathway and also decreases E-cadherin expression and increases vimentin expression; these effects are abolished by chrysophanol." (PMID 34063134, 2021).
oral cancer (continued). "Indeed, a previous study showed that inhibiting the phosphorylation of STAT3 effectively inhibited the expression of PD-L1 in oral cancer cell lines (CAL27 and FaDu) and Tgfbr1/Pten 2cKO, an HNSCC mouse model." (PMID 34063134, 2021). "Otherwise, an additional investigation into enhanced tumor immunity, which leads to the inhibition of immune evasion and cancer aggressiveness, by suppressing the up-regulated expression of PD-L1 via the reduced activation of STAT1/STAT3 signaling, is worth pursuing in oral cancer cell lines." (PMID 34500779, 2021). "Therefore, the relationship between the STAT3 pathway and oral cancer cell apoptosis remains to be further confirmed." (PMID 34769290, 2021). "Therefore, chrysophanol has the potential to inhibit migration/invasion and EMT through the inhibition of IL-6- and IL-8-induced activation of STAT3 in oral cancer." (PMID 34063134, 2021). "Furthermore, TW-37 potentiated chemosusceptibility of cryptotanshinone in human oral cancer cell lines by suppressing STAT3–Mcl-1 signaling compared with either TW-37 or cryptotanshinone alone, resulting in potent apoptosis." (PMID 32863764, 2020). "Overall, this study highlights that targeting STAT3 using TW-37 could be an attractive approach in enhancing the prognosis of patients with oral cancer in the future." (PMID 32863764, 2020). "These pronounced effects on STAT3 could be important contributors to ME’s suppression of oral cancer." (PMID 32264893, 2020). "Hence, this study suggests that TW-37 potentiates the apoptotic effect of cryptotanshinone in human oral cancer cell lines by suppressing STAT3–Mcl-1 signaling." (PMID 32863764, 2020). "Thus, we strongly suggest that the inhibition of STAT3 is a common effect of NC in human oral cancer cell lines." (PMID 29207645, 2017). "In addition, our results revealed that NC inhibited STAT3 phosphorylation in human oral cancer cell lines." (PMID 29207645, 2017). "Prior studies established constitutively active AP‐1, NF‐κB, and STAT3 signaling in oral cancer." (PMID 28155253, 2017). "miR-21 expression is triggered by STAT3 in oral cancer TCA8113 and TSCCA cells." (PMID 28708091, 2017). "The transcription factor STAT3 is not only persistently activated in many types of cancer, including oral cancer, but also functions as a transcription factor required for regulating genes that are involved in tumor proliferation, survival, angiogenesis, and invasion." (PMID 25816241, 2015). "We previously reported that activated IL-6 pathways could be responsible for more aggressive tumor growth noted in oral cancer, and high activated STAT3 and p-AKT level was induced by IL-6 and linking IL-6 to tumorigenesis." (PMID 24625449, 2014). "In addition, work from Tumbar’s laboratory has shown that RUNX1 overexpression leads to STAT3 activation and is necessary for skin and oral cancer growth." (PMID 24967588, 2014). "Consequently, the study explored the effects of STAT3 on inflammation in oral cancer cells." (PMID 40444012, 2025). "Besides, CCL18 could facilitate the proliferation of oral cancer cells through the JAK2/STAT3 signaling pathway." (PMID 36850011, 2023). "Thus, our findings indicate that the decreased expression of Mcl-1 protein induced by TW-37 in human oral cancer cell lines could arise from the inhibition of STAT3 activation and nuclear translocation, thereby validating H1 of this study." (PMID 32863764, 2020). "We previously illustrated that the phosphorylated STAT3 levels markedly elevated in tissues obtained from patients with oral cancer compared with tissues obtained from the healthy oral mucosa, suggesting that p-STAT3 is a good prognostic indicator of oral cancer." (PMID 32863764, 2020). "Hence, this study aims to explore whether TW-37 could be a valuable therapeutic option as monotherapy in human oral cancer, as well as combination therapy with cryptotanshinone, by targeting STAT3–Mcl-1 signaling." (PMID 32863764, 2020).
oral cancer (continued). "Accordingly, STAT3 inhibitor may inhibit the function of oncogenic miR-21 in oral cancer therapy." (PMID 28708091, 2017). "Similarly, phospho‐STAT3 (Y705), an active member of STAT3 signaling was detected in oral cancer." (PMID 28155253, 2017). "Thus, STAT3 might be a potential therapeutic target for the treatment of oral cancer as well as other tumors." (PMID 29207645, 2017). "In another study, F. nucleatum upregulated MMP1, MMP9, and IL-8 in oral cancer cell lines, and the infected cell lines showed overexpression of cell survival markers, such as MYC, JAK1 and STAT3, and EMT markers (ZEB1 and TGF-β)." (PMID 40002861, 2025). "The silencing of STAT3 by shRNA inhibited the proliferation of the SAS oral cancer cell line and reduced tumor growth in the xenograft oral cancer model." (PMID 38067351, 2023). "Transfection of oral cancer cells with MEK, ERK, and STAT3 inhibitors and their small interfering RNAs inhibited CCL4-induced promotion of Angpt2 expression and angiogenesis." (PMID 35884919, 2022). "In conclusion, hesperidin exerted anticancer effects against oral cancer cells through the suppression of PD-L1 expression via inactivation of the STAT1 and STAT3 signaling molecules." (PMID 34500779, 2021). "In conclusion, heteronemin induced antiproliferation in oral cancer cells by inhibiting activation of ERK1/2 and STAT3." (PMID 32630719, 2020). "Results reported here indicate that heteronemin induces antiproliferation in oral cancer cells by inhibiting activation of extracellular signal-regulated kinase 1/2 (ERK1/2) and STAT3." (PMID 32630719, 2020). "Accordingly, we measured the expression of STAT3, JAK1, and MYC in three oral cancer cell lines (OQ01, HN, BHY) after polymicrobial infection with the combination of P. gingivalis, F. nucleatum, T. denticola, and T. forsythia by qRT-PCR." (PMID 33391626, 2020). "We observed both in vitro and in vivo oral cancer model systems a marked decrease in OSCC proliferation, cell signaling (STAT3, AKT, and ERK1/2), and circulating pro-cancer cytokines (tumor-secreted and host)." (PMID 31572681, 2019). "Constitutively active STAT3 signaling has been documented in human cancers including HCC and oral cancer." (PMID 31771617, 2019). "Blueberry and malvidin for STAT-3 inhibitors in the oral cancer cell line SCC131, which regulates downstream targets that influence cell proliferation and apoptosis by abolishing the JAK/STAT-3 signaling pathway in a hamster model of oral oncogenesis." (PMID 30223619, 2018). "Statistical evaluation of different grades for STAT3 and pSTAT3 expression with HPV positivity showed an inverse correlation of STAT3 and pSTAT3 expression with HPV infection in oral cancers." (PMID 28155253, 2017). "Previously, we reported that activation of IL-6/STAT3 signaling induced aggressive tumor behavior and EMT changes in oral cancer." (PMID 24625449, 2014). "To rule out the possible influence of chemotherapy on the activation of EUDAL/EGFR/STAT3/autophagy axis, we collected tumor samples from an additional 45 oral cancer patients who did not receive chemotherapy." (PMID 40940319, 2025). "Notably, EZH2 emerges as a significant gene involved in regulating the STAT3/HOTAIR axis, influencing HNSCC proliferation, differentiation, and promoting metastasis by modulating related oncogenes in oral cancer." (PMID 38600608, 2024). "In addition, astaxanthin hampers oral cancer cell growth, invasion, and angiogenesis by abrogating PI3K/NF-κB/STAT3 signaling pathway." (PMID 38649975, 2024). "Furthermore, we have shown the anti-tumor effect of this extract in oral cancer cells through regulation of several cell signal pathways, including AMPK, STAT3, p38 MAPK, and NF-κB." (PMID 38720012, 2024).
oral cancer (continued). "CCL4 treatment of oral cancer cells upregulated Angpt2 expression and stimulated mitogen-activated protein kinase kinase (MEK), extracellular signal-regulated kinase 1/2 (ERK), and signal transducer and activator of transcription 3 (STAT3) phosphorylation." (PMID 35884919, 2022). "Although the blueberry supplement failed to alter cellular viability in SCC131 oral cancer cells, the purified malvidin component induced a marked growth reduction (IC50 of 62 μM) associated with reduced p-JAK2 and nuclear p-STAT3 levels." (PMID 36355554, 2022). "Since STAT1/STAT3 signaling is regarded as one of the critical pathways for cell proliferation, migration, and invasion, it is likely that the anticancer effects of hesperidin are mediated by STAT1/STAT3 signaling and activated by treatment with IFN-γ in the oral cancer cell lines." (PMID 34500779, 2021). "This could be explained by the important role of CCL18 in oral cancer where it promotes hyperplasia and metastasis by JAK2/STAT3 signaling pathways." (PMID 34025655, 2021). "Our results therefore implicate potential links between the various effects of ME to inhibit oral cancer cells, including impaired complex I activity, increased ROS generation, Prx oxidation, activation of AMPK, inhibition of STAT3 and p70S6K phosphorylation, and suppression of HKII." (PMID 32264893, 2020). "Besides, TW-37 decreased the phosphorylation of signal transducer and activator of transcription 3 (STAT3) at Tyr705 and nuclear translocation in human oral cancer cell lines at the early time points." (PMID 32863764, 2020). "CCL4 stimulation of oral cancer cells augmented JAK2 and STAT3 phosphorylation." (PMID 29599774, 2018). "In addition, NC suppressed cell viability and increased cleaved PARP and caspase 3 in four other oral cancer cell lines including YD15, MC3, HN22 and Ca9.22 cells by reducing phosphorylation of STAT3." (PMID 29207645, 2017). "Notably, both STAT3 and pSTAT3 showed a concomitant increase in expression with increasing grades of lesions, particularly in HPV‐negative oral cancers." (PMID 28155253, 2017). "We demonstrated that STAT3 is constitutively phosphorylated in OSCC compared to NOM, and that NC could act as an apoptotic inducer of human oral cancer in vitro and in vivo." (PMID 29207645, 2017). "The data obtained from the present study revealed that the increased DNMT3b induced by IL-6, which might be mediated by the activation of STAT3 and PI3K signaling, is critical in tumor aggressiveness and prognosis of oral cancer." (PMID 24625449, 2014). "Furthermore, in oral cancer cell culture and animal models, P. gingivalis suppressed antigen-specific CD8+ T cells through upregulation of PD-L1 expression on dendritic cell (DC)s by increasing the phosphorylation of Akt and STAT3." (PMID 40002861, 2025). "It appears that STAT3 protein expression is mediated via the ERK pathway, while ERK activation can modulate STAT3 signaling in oral cancer, although our study results did not clearly reveal whether STAT3 is directly or indirectly activated by ERK." (PMID 35884919, 2022). "Additionally, ICAM-1 has been reported to interact with many signaling pathways in human diseases, such as ICAM-1-PI3K/Akt/GSK-3β/GATA-6 pathway in atheroscherosis, ICAM-1-IL-6/AKT/STAT3/NF-κB pathway in chronic obstructive pulmonary disease, and ICAM-1-PGE2/EP1 pathway in oral cancer." (PMID 33506255, 2021). "Based on the related literature, this study hypothesizes that the transcriptional regulation of Mcl-1 in human oral cancer cell lines upon TW-37 treatment could correlate with the signal transducer and activator of transcription (STAT) family members, including STAT3 (H1)." (PMID 32863764, 2020). "Similarly, this study found that the STAT3 inhibitor stattic further promoted LPS- and TNF-α-induced increases in cell viability and migration of oral cancer cells, highlighting the crucial role of IL-37 in regulating the growth, proliferation, and migration of oral cancer cells." (PMID 40444012, 2025).
oral cancer (continued). "Therefore, our study along with the available strong literature provides a useful combinatorial expression data of key members of AP‐1, NF‐κB, and STAT3 that participate in DNA binding and qualify as molecular signature of HPV‐positive and negative oral cancers." (PMID 28155253, 2017).